IL6 (interleukin 6)
Diseases named in the same sentence as IL6 in open-access papers (continued):
Sharing a sentence is not in itself a finding about the gene and the disease.
tumor (continued). "Immune cell infiltration of the tumor and the release of interleukins (IL), specifically IL-2, IL-6, and IL-8, tumor necrosis factors, and interferons have proven their immunomodulatory effects in a number of studies." (PMID 39507201, 2024). "Flint and colleagues demonstrated that tumor-induced IL-6 suppresses the production of hepatic ketone bodies, resulting in the significant secretion of glucocorticoids during periods of caloric deficiency." (PMID 38466657, 2024). "Here, we provide evidence that bazedoxifene inhibits tumour growth via direct interaction with the gp130 receptor to suppress IL-6 and IL-11-mediated STAT3 signalling." (PMID 38600086, 2024). "Given the role and significance of IL-6/sIL-6R trans-signaling in tumor progression, targeting this trans-signaling has therapeutic potential in many types of cancer." (PMID 38182653, 2024). "Recognizing that tumor development is influenced by multiple factors, it becomes imperative to explore combinations of IL-6 targeted drugs with other medications." (PMID 38828409, 2024). "The authors also described aggravation of inflammatory reaction by macrophage and neutrophil infiltrates and tumor-related IL-6 and TNF-α cytokines." (PMID 40135141, 2024). "It is well-known that interleukin-6 functions as a key growth factor in MM by rendering tumor cells insensitive to Fas-mediated apoptosis." (PMID 38307835, 2024). "IL-6 trans-signaling in various cancer types promotes tumor progression by suppressing anti-tumor responses of immune cells as well as increasing cell growth through signal transduction in tumor cells themselves." (PMID 38182653, 2024). "Most tumor cells overexpress IL-6, and activation of the IL-6/STAT3 signaling pathway promotes tumorigenesis by regulating multiple signaling pathways implicated in the hallmarks of cancer." (PMID 39596207, 2024). "In our previous studies, we analyzed the diagnostic and prognostic value of CRP and IL-6 levels measurement in OC in relation to different histological subtypes (OSCC and OAC) and compared them with classical tumor markers: CEA and SCC-Ag." (PMID 38673838, 2024). "IL-6 plays a role in regulating tumor angiogenesis and lymphangiogenesis, contributing to tumor progression and metastasis." (PMID 38803729, 2024). "IL-6 or IL-8 secreted by tumor cells induces the activation of STAT3 in NK cells and inhibits the function of NK cells in ESCC." (PMID 38320998, 2024). "Inflammatory responses and tumor developments are closely related, with interleukin-6 (IL-6) playing important roles in both processes." (PMID 38928482, 2024). "In cancer patients, an elevated level of PCT is associated with the tumor microenvironment, characterized by an inflammatory state where tumor cells and surrounding cells produce proinflammatory mediators such as TNF-α, IL-6, and IL-1." (PMID 39797227, 2024). "Elevated neutrophil levels can both promote inflammatory mediator release, such as IL‐1 and IL‐6, fostering tumor angiogenesis and metastasis, and inhibit lymphocytes and natural killer cells, enhancing tumor immune evasion capabilities." (PMID 39140242, 2024). "Pro-inflammatory cytokines such as IL-6, IL-8, IL-31, and IL-33 promote tumor growth and resistance to apoptosis." (PMID 38464838, 2024). "We also found that IL-6 was primarily derived from the tumor stroma and fibroblast subsets in both the human and murine TMEs through bioinformatics analysis." (PMID 38459511, 2024). "Triptolide can exert anti-tumor effects on lung carcinoma cells of NSCLC by inhibiting the activation of the IL-6/STAT3 axis." (PMID 38361933, 2024). "These molecules, such as platelet-derived growth factor, fibroblast growth factor, transforming growth factor-β (TGF-β), and interleukin (IL)-6, bind to receptors on tumor cells, promoting tumor growth, differentiation, and metastasis." (PMID 38292868, 2024).
tumor (continued). "Due to the specificity of these cytokines to potentiate cancer development, IL-6 and IL-17 drive oncogenesis by regulating several signaling mechanisms important to tumor growth and inflammation." (PMID 38279220, 2024). "IL-10 has been associated with inhibiting neovascularization and tumor metastasis by downregulating the synthesis of VEGF, IL-1β, TNF-α, IL-6, and MMP-9 in tumor-associated macrophages and natural killer (NK) cell-dependent mechanisms, respectively." (PMID 38672182, 2024). "Adjuvant IL-7 enhanced T cell effector function by increasing IL-6 production and T helper type 17 cell differentiation, resulting in improved anti-tumor responses and overall survival." (PMID 38424167, 2024). "In the HCC microenvironment, IL-6 is released by the activated NF-κB pathway, and eventually, the NF-κB/IL-6/STAT3 pathway exerts a pro-tumor effect in inflammation-associated tumors, such as HCC." (PMID 38816668, 2024). "Especially in tumor microenvironment, the expression of IL-6 pathway genes was generally downregulated." (PMID 38881895, 2024). "Under cancerous conditions, IL-6 can participate in various processes such as tumor formation, cancer cell proliferation, epithelial–mesenchymal transition, interactions between tumor cells and the matrix environment, tumor dissemination, and drug resistance." (PMID 38339264, 2024). "Normally, high levels of IL-6 in the tumor microenvironment are thought to reflect the relationship between inflammation and cancer." (PMID 39317690, 2024). "In this manuscript, we propose that the relationship between IL-6 and the sex hormone E2 that was first described in the tumor microenvironment exists in the skin and contributes to dermal fibrosis." (PMID 39000334, 2024). "In a recent review article, the authors reviewed the effects of different cytokines, such as IL-2, TGF-β, IL-4, IFN-γ, IL-6, and IL-23, on the tumor microenvironment and the CAR-T cell activity." (PMID 38534922, 2024). "The combination treatment of maraviroc (CCR5 inhibitor) and tocilizumab (IL-6 inhibitor) significantly block TNBC tumor growth and metastasis." (PMID 38393465, 2024). "IL17A augments IL6 production by activating tumor-intrinsic STAT3, resulting in tumor growth and invasion." (PMID 38672199, 2024). "IL-6, a major inflammatory factor within the tumor microenvironment, is intricately involved in tumor progression, immune modulation, and inflammatory responses." (PMID 38484140, 2024). "IL-17 has also been found to promote B16 (melanoma) tumor growth by inducing IL-6 expression and activating Stat3 signaling." (PMID 39906741, 2024). "While CAFs-secreted IL6 appears to reciprocally stimulate tumor cell proliferation, sustained IL6 secretion also promotes chronic inflammation and immune evasion." (PMID 38233872, 2024). "Our computational analysis suggests that HPV − tumor cells have a stronger reliance on IL6/IL6R and CCL2/CCR2 signaling within the tumor microenvironment (TME) to evade NK cell immune attack, in contrast to HPV + tumors." (PMID 38468260, 2024). "Based on the previous studies, Cav1, MCT4, acid lactic, TGFβ, and IL-6 are crucial hallmarks of cancer, involving tumor progression and therapy resistance via promoting metabolic symbiosis." (PMID 38361760, 2024). "Interleukin-6 (IL-6) has a multifaceted role in tumor promotion, including tumor progression, proliferation, migration, apoptosis, and angiogenesis." (PMID 39519758, 2024). "Tumor-associated macrophages (TAMs) release various cytokines, including IL-8, IL-6, and IL-10, which regulate the cell cycle and promote tumor growth." (PMID 38402232, 2024). "In this context, this study aimed to find IL-6 signaling systemic abnormalities in the inflammatory tumor microenvironment." (PMID 39452544, 2024). "In the early stages, IL-6 and IL-17 work to elevate a pro-tumor effect by stabilizing the CD4+ Th17 phenotype." (PMID 38279220, 2024).
tumor (continued). "LRG1 induction in the tumor mass and systemically in cancer is most probably through IL-6 and STAT3, with contributions from other signaling pathways." (PMID 38745756, 2024). "This multifaceted approach extended to bolstering anti-tumor immunity by tempering the immunosuppressive interleukin IL-6." (PMID 38653790, 2024). "These cells produce pro-inflammatory cytokines (of particular interest are TNF-α, IL-6, and interferon), proteases, MMPs, and NETs that support inflammation and favor tumor development and metastasis." (PMID 38612841, 2024). "The complex interplay of IL6 signaling across multiple cell types makes it a promising therapeutic target in OC, offering the potential for strategies to disrupt the tumor-supportive microenvironment and enhance the efficacy of current treatments." (PMID 39766086, 2024). "TAMs in advanced breast cancers exhibited preferential FABP4 expression, promoting tumor growth via IL6/STAT3 signaling." (PMID 38185636, 2024). "Meanwhile, the production of persistent chronic inflammatory mediators such as interleukin‐6 (IL‐6) increases tumour migration and invasion." (PMID 38961677, 2024). "The Bi + mAb treatment increased the serum levels of IL-6 as well as TNF-α levels at the tumor site, which mediated inflammation." (PMID 39010088, 2024). "A recent study found that the combination of anti-CD40 antibody and anti-IL-6 antibody for glioblastoma reversed TAMs to a tumor-killing phenotype, more effectively inhibiting tumor progression." (PMID 39403370, 2024). "This included pro-inflammatory cytokines such as IL6 and IL8, typically elevated in the tumor microenvironment, and TNF-alpha, known for its association with T-cell activation." (PMID 38383454, 2024). "Mechanistically, VPS35 activated FAK-SRC kinases through integrin-mediated outside-in signalling, leading to the activation of YAP and subsequent IL-6 expression induction in tumour cells." (PMID 37950040, 2024). "Probiotic strains and bacterial CFSs that promote generalized mucosal immune responses via proinflammatory cytokine production (e.g., TNF-α, IL-1β and IL-6) were found to fortify the host defense system and provide anti-pathogen and anti-tumor effects." (PMID 39534506, 2024). "β2-Adrenoceptors in tumor-associated macrophages contribute to HCC progression through activating cAMP/PKA/CREB and cAMP/IL6 signaling pathways." (PMID 38233872, 2024). "Studies in animal models have found that epinephrine and IL-6 mediated mobilization of NK cells during exercise decreases tumor size, and that administration of lactate reduces tumor growth in cytotoxic T cell-dependent manner." (PMID 38979417, 2024). "Conversely, 2‐ME‐treatment resulted in fewer CD163+ cells detectable in the TME, increased levels of tumor necrosis, increased IL‐10 plasma levels, and low IL‐6 and IL‐27 plasma levels." (PMID 38600057, 2024). "Inflammatory molecules such as IL-6 and IL-8 are secreted by the tumor cells themselves or by the surrounding stromal cells and adipose tissue, enhancing tumor growth and metastasis." (PMID 39338222, 2024). "In the tumor microenvironment, large amounts of pro-inflammatory cytokines, such as interleukin-6 (IL-6) and tumor necrosis factor-α (TNF-α), are secreted." (PMID 39687887, 2024). "Curcumin treatment reduced the percentages of MDSCs in the spleen, blood, and tumor tissues, decreased IL-6 levels in serum and tumor environments, and inhibited MDSC proliferation." (PMID 39906672, 2024). "The lower concentrations of pro-inflammatory cytokines IL-1β and IL-6 in SAADKO tumor-bearing mice suggest a diminished inflammatory response, which is consistent with findings from our previous CAC study." (PMID 39336082, 2024). "The mechanism, in which IL-6 signaling contributes to tumor progression and metastasis and regulates other cytokines, can be both autocrine and paracrine." (PMID 39201656, 2024).
tumor (continued). "In conclusion, this study showed that IL-6 induces CD155 expression in tumor cells and identified SOCS1 as a negative regulator of this process." (PMID 39596207, 2024). "There are several reports on the discrepancy between the presence of IL-6 in tumor tissue and serum." (PMID 39518029, 2024). "This culminates in heightened production of interleukin-6 (IL-6) and interleukin-8 (IL-8), which enhance invasion of tumor cells." (PMID 39696702, 2024). "Therapeutically, gp130 blocker SC144 was added to investigate the contribution of IL-6/STAT3 signaling to tumor progression in subcutaneous LLC and BMDM co-implantation models in vivo." (PMID 38274367, 2024). "The dysregulation of IL-6 stimulates tumor growth and progression and also establishes a pro-tumorigenic microenvironment." (PMID 38276239, 2024). "Physical activity also triggers the secretion of substances, such as myokines IL‐15 or IL‐6 within muscle tissue, initiating the redistribution of immune cells and eventual infiltration of the tumor site to eradicate tumor cells." (PMID 38234174, 2024). "For instance, anti-IL-6 antibodies at least partly eliminated the exercise-induced tumor suppression observed in mice." (PMID 38928185, 2024). "M1 macrophages produce pro-inflammatory cytokines (e.g., tumor necrosis factor-α and IL-6) and induce anti-tumor immune responses." (PMID 39684424, 2024). "Clorgyline, a MAOA inhibitor, effectively suppresses tumor development in mice, increasing caspase three levels and decreasing IL-6, pSTAT3, STAT3, and CD44 production in tumor cells." (PMID 39092186, 2024). "IL-6 blockade sensitized EGFR-mutant GEMM tumors to PD-1 inhibitors by increasing tumor-infiltrating IFNγ+ CD8+ T cells." (PMID 39015563, 2024). "On the other hand, continuous IL-6 blockade from tumor onset also effectively decreased ongoing pain and tumor-induced bone remodeling." (PMID 38940936, 2024). "Our in vivo studies show that human IL6-alone-expressing NSG mice are permissive to the engraftment and organ colonization of the U2932 ABC and VAL GCB DLBCL cells, strongly indicating that IL6 is sufficient for systemic DLBCL tumor growth." (PMID 39272864, 2024). "This study showed that GMI’s tumor-suppressive action was achieved by blocking IL-6/Stat3 signaling." (PMID 39272862, 2024). "IL-6 facilitates communication between endothelial cells and tumor cells through chemokines, promoting the transendothelial migration of cancer cells." (PMID 38803729, 2024). "No or very low levels of other cytokines found post-TCE treatment such as interleukin (IL)-6 and IL-10 were detected in the tumor supernatant." (PMID 39261676, 2024). "Our previous work with the 4T1 model reported that these tumors can skew the host adaptive immune milieu toward a Type 3 (Th17) immune module, dependent on tumor cell expression of IL-6." (PMID 39195287, 2024). "In tumour microenvironments, cancer cells increase B7-H4 expression in response to hypoxia and transforming growth factor β1 (TGFβ1); IL-6 and IL-10 can also stimulate B7-H4 mRNA expression in macrophages." (PMID 39571901, 2024). "Signal transmission through the IL-6 trans-signaling pathway is important in stimulating nearly every type of cell in the body, including intestinal epithelial cells, as well as tumor cells." (PMID 39199686, 2024). "Playing a vital role as the central cytokine within the body, IL-6 also participates in regulating the immune response within the tumor microenvironment and promoting tumor proliferation." (PMID 38564670, 2024). "For instance, chronic inflammation often involves immune cells such as macrophages that secrete Interleukin-6 (IL-6), which facilitates the formation of the tumor microenvironment (TME)." (PMID 39450166, 2024). "High systemic IL6 levels are associated with adverse clinicopathological characteristics in CRC, including advanced T stage and tumour necrosis." (PMID 39766336, 2024).
tumor (continued). "M1 can enhance the expression of MHC-II+, TNF-a, IL-1β, and IL-6, enhance the production of reactive oxygen species and NO, and have certain tumor damage activity." (PMID 39351151, 2024). "The roles of IL-6 in tumour progression and immunosuppression have been discussed, and the immunostimulatory roles of cytokines like IFN-γ, IL-2, and TNFα in cancer biology are also known." (PMID 38473281, 2024). "IL-6 promotes cancer progression by regulating tumor markers and multiple signaling pathways, including apoptosis, survival, proliferation, angiogenesis, invasion, and metastasis, as well as metabolism." (PMID 38533503, 2024). "In turn, Tc17-iCAFs support the differentiation of T cells towards the Tc17 phenotype and promote tumor growth relentlessly through the secretion of IL-6." (PMID 39680287, 2024). "Immune cells produce pro-inflammatory mediators such as TNF-α, IL-6, IL-1, IL-12, and iNOS, leading to reprogramming the immunosuppressive tumor microenvironment into an immunogenic one to aid in the elimination of tumors." (PMID 38974834, 2024). "We detected IL-6 and M-CSF, present in tumor-CM and patient serum, as inducers of CD14+ cDC2s from cDC2s." (PMID 38242119, 2024). "It is clear that IL-6 regulates macrophages, T cells and other immune cells, it has closely connection with tumor immunosuppressive microenvironment." (PMID 39654892, 2024). "Under the influence of IFN‐γ, IL‐6, and so forth, M1 macrophages can inhibit tumor cells by releasing soluble enzymes, TNF and IFN and activating T cell immune responses, showing proinflammatory, antigen presentation and antitumor effects." (PMID 39233637, 2024). "IL-6 has also been shown to promote the differentiation of regulatory T cells, which suppress the immune response and promote tumor growth, although the relevance of this finding in the peritoneal cavity remains to be assessed." (PMID 38689325, 2024). "For instance, tumor-derived IL-6 and M-CSF convert immature DCs into macrophages and prevent the priming of tumor-specific T cells." (PMID 38520006, 2024). "Among these factors, IL-6 is secreted by the tumor cells that activates the STAT3 in LECs and ultimately upregulates the VEGF expression, which is a necessary element for lymph angiogenesis." (PMID 38361941, 2024). "The analysis revealed elevated levels of pro-inflammatory cytokines, including interleukin-6 (IL-6) and tumor necrosis factor-alpha (TNF-α), which are often linked to chronic inflammation and tumor progression." (PMID 39795579, 2024). "Pro-inflammatory cytokines like IL-1, IL-6, and TNF-α, produced by various cell types including immune cells (e.g., macrophages and T cells), cancer-associated fibroblasts (CAFs), and tumor cells themselves, promote inflammation and tumor cell proliferation." (PMID 39200315, 2024). "OCa-associated mesenchymal stem cells are shown to secrete IL6 and LIF to induce tumor cell stemness." (PMID 38789520, 2024). "T-reg also supports tumorigenesis by enriching GSC populations by secreting TGF-β, which in turn promotes tumor cells to secrete IL6 that induces stemness in glioblastoma cells." (PMID 38256140, 2024). "Similar results were observed in prostate cancer where gut dysbiosis increased gut permeability and intratumoral LPS which promotes tumor progression via NF-κB/IL6/STAT3 axis." (PMID 38520006, 2024). "The presence of the HPV has been associated with increased inflammatory cytokines (IL-1, IL-6, IL-17, TGF-β, TNF-α, and NF-kB) and tumor progression." (PMID 38994984, 2024). "Several studies have shown that inflammatory cytokines, including IL-1, IL-6, TNF-α, and IL-25, are crucial in increasing tumor-associated inflammation, metastasis, angiogenesis, and apoptotic induction." (PMID 39267848, 2024). "This HLF expression was dependent on TAM-derived TGF-β1 secretion, which was further supported by tumor cell IL-6 secretion." (PMID 39188677, 2024).